ITGB8 (integrin subunit beta 8)
Diseases named in the same sentence as ITGB8 in open-access papers (continued):
Sharing a sentence is not in itself a finding about the gene and the disease.
infection (4 papers, 2013 to 2025). The state of being infected such as from the introduction of a foreign agent such as serum, vaccine, antigenic substance or organism. "Strikingly, and despite the maintained Th2 and Th9 response in Itgb8 (CD11c-Cre) mice, we observed a significant delay in worm expulsion and exacerbated weight loss following infection, as compared to wild-type mice." (PMID 30998782, 2019). "Strikingly, Itgb8 (CD11c-Cre)×IL-4−/− mice were completely susceptible to infection, with parasite burdens comparable to those seen in control mice." (PMID 24098124, 2013). "Although we did see some increased morbidity in terms of weight loss during the infection of Itgb8 (CD11c-Cre) mice, our adoptive transfer experiments suggest this is most likely due to the decreased Treg population and possibly the increased worm burden phenotype seen." (PMID 30998782, 2019). "Strikingly, Itgb8 (CD11c-Cre) mice were completely protected from chronic infection by T. muris at day 35 post-infection, with mice showing protection as early as day 14 post-infection." (PMID 24098124, 2013). "In the absence of total lymphocytes, protection from infection was completely absent, with Itgb8 (CD11c-Cre) SCID−/− mice showing similar susceptibility to infection as control mice." (PMID 24098124, 2013). "Indeed, protection from infection observed in Itgb8 (CD11c-Cre) mice was even more pronounced than that observed using antibody-mediated blockade of TGFβ function." (PMID 24098124, 2013). "Interestingly, the increase in TGFβ signalling observed in CD4+ T-cells early during T.muris infection was significantly reduced in Itgb8 (CD11c-Cre) mice, with pSmad2/3 levels remaining similar to those observed in uninfected mice during the first week of infection." (PMID 24098124, 2013). "Absence of CD4+ T-cells restored susceptibility to infection in Itgb8 (CD11c-Cre) mice." (PMID 24098124, 2013). "Additionally, to directly assess whether reduced Foxp3+ Treg numbers Itgb8 (CD11c-Cre) mice was responsible for protection from infection, we rescued Treg numbers by adoptively transferred Foxp3+ Tregs from GFP-Foxp3 mice prior to infection." (PMID 24098124, 2013). "In contrast, although there was a slight enhancement of the Th1 cytokine IFNγ 3 days post-infection, this was not significantly different between control and Itgb8 (CD11c-Cre) mice." (PMID 24098124, 2013). "We also observed a slight increase in IFNγ+ lamina propria CD4+ T-cells in Itgb8 (CD11c-Cre) mice early post-infection; however, these levels were not significantly different from those seen in control mice." (PMID 24098124, 2013). "Importantly, mice lacking integrin αvβ8 on DCs (Itgb8 (Cd11c-cre)) have a delayed ability to expel the intestinal stage of the infection, despite an equivalent Th2 response to wild-type controls." (PMID 30998782, 2019). "As both control mice and Itgb8 (CD11c-Cre) mice did not display production of IL-4 early during T. muris infection, these mice allowed us to test the role of the enhanced IL-13 response seen early during infection in Itgb8 (CD11c-Cre) mice." (PMID 24098124, 2013). "Thus, to determine the importance of this pathway in promoting TGFβ signalling in CD4+ T-cells during T. muris infection, we analysed T-cell responses in C57BL/6 control mice and mice lacking integrin αvβ8 on DCs (Itgb8 (CD11c-Cre) mice) during infection." (PMID 24098124, 2013). "In contrast, we did not observe any differences in pSmad2/3 induction in dendritic cells between control and Itgb8 (CD11c-Cre) mice, indicating that the integrin αvβ8-mediated TGFβ activation does not trigger autocrine TGFβ signalling in DCs during early infection." (PMID 24098124, 2013). "Thus, an alternative explanation for the expulsion of a normally chronic infection of T. muris by Itgb8 (CD11c-Cre) mice is that, in the absence of early CD4+ T-cell TGFβ signalling, mice produce a Th2-type response instead of the usual non-protective Th1 response." (PMID 24098124, 2013).
infection (continued). "In contrast to Itgb8 (CD11c-Cre) mice, Itgb8 (CD4-Cre) mice showed no protection from infection with T.muris and showed an identical parasite-specific IgG2a/IgG1antibody bias which is associated with development of a chronic infection." (PMID 24098124, 2013). "Indeed, in contrast to Itgb8 (CD11c-Cre) mice, no enhancement of CD4+ T-cell IL-13 production was observed early during infection in Foxp3+ Treg-depleted mice." (PMID 24098124, 2013).
immune disorder (2 papers, 2018 to 2024). "The down-regulation of integrin subunit beta 8 (ITGB8) was observed, suggesting the interruption in alpha-V/beta-8-mediated TGF-β activation through dendritic cells which is vital for preventing immune disorder." (PMID 29503661, 2018).
cardiovascular disease (1 paper, 2025). "Comparative transcriptomic analysis revealed that genes related to cardiovascular disease (e.g., Sgcb, Adcy2, Itga1, Itgb8, Ifng, and Gpc1) were upregulated in the livers of R. pruinosus compared to carnivorous and omnivorous rodents, indicating a higher cardiovascular disease risk." (PMID 40941321, 2025).
heart disease (1 paper, 2017). "Some of those genes, including ITGA4, ITGB8, MYL7, ITGB7, HIF-1α and BNP, are assosiated with heart disease pathways and are recognized as myocardial injury biomarkers." (PMID 28692647, 2017).
neurodegenerative disease (1 paper, 2025). A disorder of the central nervous system characterized by gradual and progressive loss of neural tissue and neurologic function. "Combining mouse models of neuroinflammatory or neurodegenerative disease with brain region-specific Itgb8 conditional knock-out models will be especially illuminating." (PMID 40121230, 2025).
ITGB8 also shares sentences with these, for which no sentence is quoted: gastric cancer (3 papers); pancreatic cancer (2); amyloid (1); arrhythmogenic right ventricular cardiomyopathy (1); cardiomyopathies (1); cleft palate (1); colon carcinoma (1); endometriosis (1); epilepsy (1); esophageal cancer (1); Focal cortical dysplasia (1); glomerulosclerosis (1); Hepatitis (1); Hypertension (1); hypertrophic cardiomyopathy (1); intracerebral hemorrhage (1); ischemia (1); kidney failure (1); laryngeal squamous cell carcinoma (1); lymph node metastasis (1); mastocytosis (1); myocarditis (1); Obesity (1); osteonecrosis (1); pancreatic ductal adenocarcinoma (1); prostate tumor (1); prostatic intraepithelial neoplasia (1); Splenomegaly (1); systemic sclerosis (1).